RAD18 (RAD18 E3 ubiquitin protein ligase)
Description:
E3 ubiquitin-protein ligase involved in postreplication repair of UV-damaged DNA. Postreplication repair functions in gap-filling of a daughter strand on replication of damaged DNA. Associates to the E2 ubiquitin conjugating enzyme UBE2B to form the UBE2B-RAD18 ubiquitin ligase complex involved in mono-ubiquitination of DNA-associated PCNA on 'Lys-164'. Has ssDNA binding activity.
Synonyms: RNF73
Tractability: PROTAC: UniProt records ubiquitination sites on it; ubiquitination databases record sites on it.
Target class: Enzyme; Transferase
Gene: Protein-coding gene on chromosome 3 (8,775,402 to 8,963,773, reverse strand). Ensembl gene ENSG00000070950.
Subcellular location: Nucleus; Cytoplasm, cytoskeleton, microtubule organizing center, centrosome
Subcellular location (Human Protein Atlas): Nuclear bodies; Nucleoplasm; Nuclear speckles
Pathways (Reactome):
DNA Repair: Recognition of DNA damage by PCNA-containing replication complex
Metabolism of proteins: E3 ubiquitin ligases ubiquitinate target proteins
Gene Ontology:
Molecular function: identical protein binding; polyubiquitin modification-dependent protein binding; protein binding; protein-containing complex binding; ubiquitin protein ligase binding; Y-form DNA binding; damaged DNA binding; DNA binding; single-stranded DNA binding; ubiquitin protein ligase activity
Biological process: DNA damage response; positive regulation of chromosome segregation; protein autoubiquitination; DNA damage tolerance; DNA repair; protein monoubiquitination; protein ubiquitination
Cellular component: centrosome; nuclear body; nuclear inclusion body; nuclear speck; nucleoplasm; nucleus; replication fork; site of double-strand break; Rad6-Rad18 complex; chromosome
Genetic constraint (gnomAD): Loss-of-function variants: 31 observed, 39.84 expected, observed/expected ratio (o/e) 0.78, 90% interval 0.58 to 1.05. The upper end of that interval is the gene's LOEUF score, 1.05, which puts it in group 4 of 6, group 1 being the genes least tolerant of losing a copy. Missense variants: 511 observed, 497.91 expected, observed/expected ratio (o/e) 1.03, 90% interval 0.95 to 1.1. Synonymous variants: 183 observed, 167.08 expected, observed/expected ratio (o/e) 1.1, 90% interval 0.97 to 1.24.
Homologues: Orthologues: chimpanzee RAD18 (98% identical), macaque RAD18 (96% identical), dog RAD18 (84% identical), pig RAD18 (84% identical), guinea pig RAD18 (78% identical), rat Rad18 (77% identical), rabbit RAD18 (75% identical), mouse Rad18 (74% identical), tropical clawed frog rad18 (45% identical), zebrafish rad18 (35% identical).
Diseases named in the same sentence as RAD18 in open-access papers:
RAD18 is named in the same sentence as 53 diseases in open-access papers, as found by Europe PMC text mining. Sharing a sentence is not in itself a finding about the gene and the disease. The quoted sentences say what the papers report.
colorectal cancer (9 papers, 2019 to 2025). A primary or metastatic malignant neoplasm that affects the colon or rectum. "RAD18 has also been associated with enhanced EMT in colorectal cancer and contributes to mutagenesis." (PMID 40016217, 2025). "There is a significant correlation between RAD18 SNP (Arg302Gln) gene polymorphisms and clinicopathological parameters in colorectal cancer, especially in terms of the degree of differentiation (OR = 7.00) and lymph node metastasis (OR = 3.71)." (PMID 40859476, 2025). "Here, the study was designed to mine the mechanism by which RAD18 regulates the killing effect of NK cells on colorectal cancer (CRC) cells." (PMID 38073330, 2024). "miR-145 antagonizes SNAI1-mediated stemness and radiation resistance in colorectal cancer, and reversed 5-fluorouracil (5-FU) drug resistance by directly targeting DNA damage-related gene RAD18 in colorectal cancer." (PMID 36077665, 2022). "Another recent study has found that microRNA-145 (miR-145) can suppress expression of Rad18 in colorectal cancer (CRC) cells resulting in increased levels of DNA damage after 5-FU (5-fluorouracil) treatment." (PMID 33023096, 2020). "Rad18 plays an important role during establishment of chemoresistance of colorectal cancer cells." (PMID 38528023, 2024). "This includes Rad18, responsible for PCNA monoubiquitination, which is overexpressed in colorectal cancer, melanoma, and glioma cells." (PMID 33023096, 2020).
Fanconi anemia (9 papers, 2007 to 2025). Fanconi anemia (FA) is a hereditary DNA repair disorder characterized by progressive pancytopenia with bone marrow failure, variable congenital malformations and predisposition to develop hematological or solid tumors. "To explore the mechanistic connection between RAD18 and transcriptional stress, we investigated the Fanconi Anemia pathway, due to the proposed role of RAD18 in localizing FANCL to chromatin." (PMID 36480547, 2022). "ssDNA exposure (RPA foci), translesion synthesis (RAD18 foci), and Fanconi Anaemia pathway activation (FANCD2) were all induced in DLD-1 WT, DLD-1 BRCA2KO, and SUM149PT cells, indicative of replication perturbation and invocation of replication fork recovery mechanisms." (PMID 41359388, 2025). "Replication stress is known to induce DNA damage due to the stalled or collapsed forks, which then activates ATM/ATR-mediated cell cycle checkpoint responses to promote fork stability and restart thorough Rad18 and Fanconi anemia (FA) DNA repair pathways (monoubiquitinated FANCD2)." (PMID 25742788, 2015). "The Fanconi anemia and the RAD6/RAD18 pathways are remarkably conserved both biochemically and functionally between humans and birds." (PMID 18082605, 2007). "This analysis identified several novel ATR synthetic lethal partner genes involved in DNA damage/repair including those targeting components of the HR/Fanconi Anaemia pathway (FANCE, SLX4, PALB2), DNA mismatch repair (MSH4, PMS2) and trans-lesion synthesis (RAD18) pathways." (PMID 27958275, 2016). "In contrast, two different groups recently showed that the ubiquitin ligase activity of RAD18 is required for Fanconi Anemia pathway activation at DSBs, independent of PCNA ubiquitylation." (PMID 21858012, 2011).
lung carcinoma (8 papers, 2009 to 2024). "It has been reported that polymorphisms of RAD18 were significantly associated with hematological toxicity in nonsmall cell lung cancer (NSCLC)." (PMID 35990252, 2022). "Recently, a report that the same SNP of Rad18 is associated to the risk of lung cancer was published." (PMID 19630985, 2009). "Knockdown of Rad18 in three different lung cancer cells resulted in CTH upregulation, and treatment with MG132 significantly inhibited this observation." (PMID 38802791, 2024). "The expression of CTH was upregulated after knockdown of Rad18 in lung cancer cells, and Rad18 silencing resulted in reduced ubiquitination levels and prolonged protein half-life of CTH, suggesting that CTH is a substrate for the E3 ubiquitin ligase Rad18." (PMID 38802791, 2024). "The central member of the family of TLS polymerases (REV1) upregulates SERTAD2 expressions in a Rad18-dependent manner, thereby enhancing lung cancer development." (PMID 37396042, 2023). "Functionally, the acceleration of lung cancer cell proliferation induced by overexpression of REV1 was partially reversed by deletion of Rad18." (PMID 35115490, 2022). "Functional experiments suggested that the enhancement of lung cancer cell proliferation induced by REV1 overexpression was reversed by Rad18 deletion." (PMID 35115490, 2022). "We conclude that MAGE-A4 is a specific and constitutive component of the RAD18 complex in H1299 lung carcinoma cells." (PMID 27377895, 2016). "Fragment southern blotting revealed that the genomic lesion of Rad18 was homozygously deleted in PC3 lung cancer cell line." (PMID 19630985, 2009). "Furthermore, overexpression of SERTAD2 partially reversed the suppression of lung cancer cell proliferation induced by silencing of Rad18." (PMID 35115490, 2022). "REV1 promotes lung tumorigenesis by activating Rad18/SERTAD2 signaling axis in lung cancer cells." (PMID 35115490, 2022). "In addition, overexpression of SERTAD2 partially restored the inhibitory effect of Rad18 silencing on the proliferation of lung cancer cells." (PMID 35115490, 2022). "Similar results have been shown for AITC which induced replication stress-associated DNA damage in human lung cancer cells, where FANCD2 repair protein formed foci at stalled or collapsed replication forks, ATM/ATR, Rad18, and Chk1 were activated, and γH2A.X level was elevated." (PMID 31123866, 2020). "Within the cell lines and lung cancer tissues that we examined, no Rad18 mutation was detected but a homozygous deletion in PC3 (lung cancer cell line)." (PMID 19630985, 2009). "Though there was no coding region mutation, as lung cancer cell line PC3 had a homozygous deletion in Rad18 genomic lesion and as Rad18 is mapped at chromosome 3p25 which is reported to have frequent LOH in lung cancer, we decided to analyze lung cancer tissue for Rad18 mutation." (PMID 19630985, 2009). "Except for PC3 cell line, Rad18 gene was expressed in all digestive and lung cancer cell lines." (PMID 19630985, 2009). "Western blot analysis showed that the expression of REV1, Rad18, RPA32 and REV7 was markedly elevated in several lung cancer cell lines (A549, H1299, Calu-1, and SPC-A1) compared with the normal bronchial epithelial cells HBE." (PMID 35115490, 2022). "In REV1-silenced lung cancer cells, the expression level of SERTAD2 was significantly reduced, and the expression levels of Rad18, mUb-PCNA and RPA32 were also reduced to varying degrees." (PMID 35115490, 2022). "Through IHC staining of lung adenocarcinoma and adjacent tissue samples and Western blot analysis of multiple lung cancer cell lines, we found that many important molecules in TLS (REV1, Rad18 and RPA32) were abnormally overexpressed in lung cancer." (PMID 35115490, 2022). "Compared with adjacent tissues, REV1, Rad18, RPA32 and REV7 showed higher expression in lung cancer tissues, indicating that TLS may be abnormally activated in lung cancer." (PMID 35115490, 2022).
lung carcinoma (continued). "Though the frequency of SNP was tended to be higher in NSCLC patients than healthy volunteers (57.7%), as the difference was not significant, we have concluded that there is no relation between Rad18 SNP and lung cancer development." (PMID 19630985, 2009). "From all these results, we came to a conclusion that, there is no relation between Rad18 and lung cancer development." (PMID 19630985, 2009). "Aberrantly expressed REV1 acts as a scaffolding protein to assist the interaction between the Rad18 E3 ubiquitin ligase and CTH, promoting CTH ubiquitination-mediated degradation and inducing remodeling of the amino acid metabolic microenvironment, leading to lung cancer radioresistance." (PMID 38802791, 2024).
breast carcinoma (5 papers, 2018 to 2024). "On the other hand, loss of RAD18 in tumors caused accumulation of indels resembling a mutation signature of the BRCA1-deficient breast cancer and suggesting that RAD18 plays also TLS-independent role during cancerogenesis." (PMID 38884202, 2024). "In this study, we first discovered that the expression of RAD18 was significantly higher in TNBC than in any other subtype of breast cancer, and the increased RAD18 expression is associated with higher levels of T stage and poor prognosis." (PMID 35413945, 2022). "Similar defects in fork recovery were observed in a BRCA1-deficient ovarian cancer cell line, UWB1.289 (UW, for simplicity), and in BRCA1-depleted MDA-MB-231 breast cancer cells upon loss of either RAD18 or UBC13, indicating that the observed phenotype is not cell type specific." (PMID 38943334, 2024). "To explore the role of RAD18 in breast cancer, we detected the expression level of RAD18 in multiple cancer subtypes from The Cancer Genome Atlas (TCGA) breast cancer database." (PMID 35413945, 2022). "RAD18 was especially highly expressed in breast cancer, and the average expression level of RAD18 was significantly higher in tumor samples than in normal samples (p < 0.01)." (PMID 35413945, 2022). "Specifically, TNBC, as the most aggressive subtype of breast cancer, showed the highest expression of RAD18 in both the TCGA database (p < 0.01) and GSE65194 (p < 0.001)." (PMID 35413945, 2022). "We found that, similar to loss of RAD18, UBC13 and PALB2, loss of RNF168 resulted in an increase in fork stalling in both BRCA1-deficient U2OS cells (Supplementary S4A) and BRCA1-deficient breast cancer MDA-MB-231 cells." (PMID 38943334, 2024). "RAD18 overexpression increased CD44+/CD24-BCSCs through the Hippo/YAP pathway, thus promoting breast cancer progression." (PMID 35413945, 2022). "With the exception of two neoadjuvantly treated mammary carcinomas, PLA showed moderate to strong Rad18/PCNA colocalization signals in all cases (including some IGF1R/PCNA negative cases)." (PMID 32701997, 2020). "Nevertheless, the role of RAD18 in breast cancer has not been well explored." (PMID 35413945, 2022).
glioma (5 papers, 2015 to 2024). A benign or malignant brain and spinal cord tumor that arises from glial cells (astrocytes, oligodendrocytes, ependymal cells). "Our analysis of genome sequence data from paired primary and recurrent glioma patient samples shows that low-RAD18 expression is associated with hypermutation and further hints at a role for RAD18 in suppressing TMZ-induced mutations." (PMID 38438348, 2024). "Loss of RAD18 prevents glioma cells from initiating tolerance mechanisms for TMZ-induced DNA lesions in S-phase and consequently cell death results." (PMID 35365623, 2022). "However, it caused a significant increase in TMZ-induced cell death in both LN229 and A172 glioma cell lines, demonstrating that RAD18 knockdown phenocopies the sensitization caused by HDACi in combination with TMZ exposure." (PMID 35365623, 2022). "MS-275 caused the downregulation of RAD18 in all TMZ-exposed glioma cell lines tested." (PMID 35365623, 2022). "Collectively, our results show that RAD18 mediates TMZ-resistance of glioma cells and its depletion reduces cancer cell resistance." (PMID 35365623, 2022). "Downregulation of RAD18 by HDAC inhibition prevented glioma cells from activating the DDR upon TMZ exposure." (PMID 35365623, 2022). "Having been able to rescue glioma cells from the TMZ/MS-275 induced S-phase accumulation by overexpressing RAD18-GFP, we conclude that RAD18 is required for bypassing TMZ-induced O6MeG MMR intermediates in S-phase." (PMID 35365623, 2022). "The mass spectrometry data showed that HDACi causes the downregulation of RAD18 and UBE2A, an E3 ubiquitin ligase and an E2 ubiquitin-conjugating enzyme respectively, in TMZ-exposed glioma cells." (PMID 35365623, 2022). "Inhibition of class I HDACs suppresses the expression of the E3 ubiquitin-protein ligase RAD18 in glioma cells." (PMID 35365623, 2022). "Lastly, RAD18 or O6-methylguanine-DNA methyltransferase (MGMT) overexpression abolished the sensitization effect of HDAC inhibition on TMZ-exposed glioma cells." (PMID 35365623, 2022). "In conclusion, glioma cells require RAD18 for the bypass of the TMZ-induced DNA lesion O6MeG by a mechanism that involves the ubiquitination of PCNA and the activation of the TMZ-induced DDR." (PMID 35365623, 2022). "Of interest, the RAD18 expression level in gliomas is an indicator for the poorer overall survival of patients suffering from this disease." (PMID 35365623, 2022). "Making use of mass spectrometry we found that MS-275 causes a decrease in the protein expression of the E3 ubiquitin ligase RAD18 in glioma cells." (PMID 35365623, 2022). "Having shown that downregulation of RAD18 sensitizes glioma cells against TMZ-induced cell death, next we analyzed whether overexpression of RAD18 would protect these cells." (PMID 35365623, 2022). "In human glioma cells, RAD18 was found to disrupt HR repair and mediate resistance to IR." (PMID 35426246, 2022). "As HDACi sensitizes different glioma cell lines by attenuating RAD18 expression, the question arose whether patient-derived glioma initiating cells would also be affected by MS-275 exposure." (PMID 35365623, 2022). "By targeting different substrate molecules, Rad18 induces radioresistance formation in various tumors such as glioma, hepatocellular carcinoma, and esophageal carcinoma, suggesting that Rad18 may be a key mediator in REV1 regulating downstream gene expression and exerting function." (PMID 38802791, 2024). "Furthermore, it was shown that RAD18 might decrease apoptosis and increase cell proliferation in glioma cells, as well as facilitate resistance to radiation exposure." (PMID 35426246, 2022). "Whether HDACs regulate the expression of RAD18 through E2F3 in gliomas is still unknown." (PMID 35365623, 2022).
glioma (continued). "Analysis of TCGA data revealed that low-grade glioma patients with high-level expression of RAD18 and POLK showed reduced survival probability when compared with RAD18-low and POLK-low groups respectively." (PMID 38438348, 2024). "In this study, it was shown that RAD18 protects glioma cells from entering TMZ-induced cell death, as the siRNA-mediated knockdown of RAD18 sensitized glioma cells towards TMZ treatment and exogenous overexpression of RAD18 prevented TMZ-induced cell death." (PMID 35365623, 2022).
osteosarcoma (5 papers, 2016 to 2024). A usually aggressive malignant bone-forming mesenchymal neoplasm, predominantly affecting adolescents and young adults. "Exo-miR-150 targets IGF2BP1, Exo-miR-195 targets KIF4A, Exo-miR-206 targets NRSN2, and RGD-Exo targets Rad18, along with other pathways that impede the evolution of osteosarcoma." (PMID 39605980, 2024). "In human osteosarcoma cell lines, it was shown that RAD18 is a transcriptional target for the transcription factor E2F3." (PMID 35365623, 2022). "We designed siRad18 to knock down the expression of Rad18 in osteosarcoma tissues." (PMID 35459258, 2022). "RAD18 expression was also MAGE-A4 dependent in H157 and H650 adenocarcinoma cells and in U2OS osteosarcoma cells (which express endogenous MAGE-A4)." (PMID 27377895, 2016).
ovarian carcinoma (5 papers, 2016 to 2025). A malignant neoplasm originating from the surface ovarian epithelium. "We then utilized a curated human ovarian cancer Tissue Microarray (TMA), containing WT, BRCA1-mutated, and BRCA2-mutated ovarian serous carcinoma sections to test whether the RAD18-dependent fork recovery pathway is upregulated in BRCA1 mutant tumors by immunohistochemical (IHC) analysis." (PMID 38943334, 2024). "Notably, treatment with an ATR inhibitor disrupted the DDUP/RAD18 interaction and abolished the effect of DDUP on prolonged DNA damage signaling, which resulted in the hypersensitivity of ovarian cancer cells to cisplatin-based therapy in vivo." (PMID 37633920, 2023). "Data from The Cancer Genome Atlas (TCGA) revealed that RAD18 mRNA is more highly expressed in BRCA1-mutated breast tumors, relative to BRCA2-mutated and WT tumors (left), although RAD18 mRNA expression does not appear to be significantly enriched in BRCA1-mutated ovarian carcinomas (right)." (PMID 38943334, 2024).
gastric cancer (4 papers, 2021 to 2025). A primary or metastatic malignant neoplasm involving the stomach. "Inhibition of RAD18 has also been found to suppress gastric cancer progression and sensitize gastric cancer to chemotherapy via reduction of PCNA mono-ubiquitination." (PMID 34671219, 2021). "Moreover, aberrant overexpression of RAD18 is common across a broad spectrum of cancers, including esophageal cancer and gastric cancer (GC)." (PMID 37728310, 2023).